HGF (hepatocyte growth factor)
Diseases named in the same sentence as HGF in open-access papers (continued):
Sharing a sentence is not in itself a finding about the gene and the disease.
ameloblastoma (2 papers, 2022 to 2024). The most common odontogenic tumor, arising from the epithelial component of the embryonic tooth and usually affecting the molar-ramus region of the mandible or maxilla. "Our data with the HGF stroma is consistent with previously published work on how stromal cells promote ameloblastoma invasion in other 3D models." (PMID 36452176, 2022). "The same expression profile was observed in 3D ameloblastoma tumouroids with HGF stroma." (PMID 36452176, 2022). "This might be due to higher soluble RANKL production in ameloblastoma tumouroids with HGF stroma." (PMID 36452176, 2022).
amyloidosis (2 papers, 2025). A disorder characterized by the localized or diffuse accumulation of amyloid protein in various anatomic sites. "In amyloidosis patients, elevated HGF levels were associated with worse survival rate at median follow-up of 2.6 years, and had higher prognostic accuracy than NT-proBNP and troponin-T (P < 0.001)." (PMID 40041176, 2025). "The limited number of patients with HF without amyloid etiology prevented comparison of the discriminatory capacity of HGF between patients with CA and patients with HF without CA." (PMID 40570404, 2025). "In addition, levels of CXCL9 and HGF were higher in patients with ATTR-CM than in patients with HF without amyloidosis." (PMID 40570404, 2025). "Importantly, levels of HGF were also higher in patients with ATTR-CM than in patients with HF without amyloidosis." (PMID 40570404, 2025).
anemia (2 papers, 2011 to 2021). A reduction in the number of red blood cells, the amount of hemoglobin, and/or the volume of packed red blood cells. "Although hypokalemia, anemia, a decrease in platelet count, prolonged PT, a decrease in anti-thrombin III, and hematuria were also observed in three of four patients, there was no apparent evidence for a causal relationship between these adverse events and rh-HGF administration." (PMID 21548996, 2011).
angiosarcoma (2 papers, 2015 to 2022). A malignant tumor arising from the endothelial cells of the blood vessels. "Interestingly, we could demonstrate that MET as well as HGF overexpression occurs in both post-radiation and primary angiosarcomas." (PMID 25844809, 2015). "We demonstrate that a subset of angiosarcomas and undifferentiated pleomorphic sarcomas (UPS) harbor MET amplifications, MET copy number gains or show MET/HGF overexpression." (PMID 25844809, 2015). "Our preliminary data on HGF expression, however, are promising since we could demonstrate a statistically significant correlation between HGF and MET overexpression namely in angiosarcomas and undifferentiated pleomorphic sarcomas." (PMID 25844809, 2015).
appendicitis (2 papers, 2021 to 2026). Acute inflammation of the vermiform appendix. "Compared to uncomplicated appendicitis, complicated appendicitis showed statistically significantly elevated levels in interleukin 6 (IL-6) (p < 0.001), hepatocyte growth factor (HGF) (p = 0.003), and monocyte chemoattractant protein 1 (MCP-1) (p < 0.001)." (PMID 41711118, 2026).
Arrhythmia (2 papers, 2011 to 2014). Any cardiac rhythm other than the normal sinus rhythm. "While the arrhythmia score for evoked VA in the PBS group was quite high, this score was significantly reduced in the HGF-MSC and MSC groups (HGF-MSC group 1.11±1.17 vs. PBS group 4.90±1.37, P<0.01; MSC group 2.56±1.13 vs. PBS group 4.90±1.37, P<0.01)." (PMID 25360679, 2014).
arteriosclerosis (2 papers, 2024 to 2025). A vascular disorder characterized by thickening and hardening of the walls of the arteries. "One potential concern when using HGF agonists as therapeutic agents is their impact on the cardiovascular system, such as the increased risk of endothelial deposition and arteriosclerosis due to the mobilization of lipids from the liver into the bloodstream." (PMID 39108737, 2024). "Studies have demonstrated that inflammatory mediators such as fractalkine/CX3CL1, CCL8, M-CSF, HGF, E-selectin, PI3/elafin, CCL17, and IL-16 are significantly elevated in patients with AD, contributing to the progression of arteriosclerosis." (PMID 40757030, 2025).
Ascites (2 papers, 2023). Accumulation of fluid in the peritoneal cavity (between the layers of the peritoneum that lines the abdomen). "HGF increases their survival and proliferation, while simultaneously promoting fibrosis and diffuse infiltration, leading to peritoneal carcinomatosis and ascites." (PMID 37834127, 2023). "The combination of inflammatory markers and clinical variables favoured five inflammatory markers (TWEAK, CCL4, HGF, TRANCE and IL-33) and one clinical variable (ascites) with an AUROC of 0.73 and 95% CI [0.57;0.88]." (PMID 37973887, 2023).
autism spectrum disorder (2 papers, 2017 to 2021). A spectrum of developmental disorders that includes autism, and Asperger syndrome. "In this review, we highlight, beyond the neurotrophic action, novel roles of HGF-MET in synaptogenesis during post-natal brain development and the connection between deregulation of MET expression and developmental disorders such as autism spectrum disorder (ASD)." (PMID 34179015, 2021).
autoimmune encephalitis (2 papers, 2021 to 2024). Inflammation of the brain secondary to an immune response triggered by the body itself. "Inflammatory factors that may be causally associated with autoimmune encephalitis are C-C motif chemokine 25 levels and hepatocyte growth factor levels." (PMID 40008261, 2024). "In mice, HGF overexpression in neurons increased Treg percentage in the central nervous system and inhibited the development of experimental autoimmune encephalitis." (PMID 34771724, 2021).
bacteremia (2 papers, 2017 to 2025). "The presence of bacteremia was associated with low concentrations of HGF (p = 0.005), IL-15 (p = 0.002), IL-6 (p = 0.05), IP-10 (p = 0.008), MIG (p = 0.03) and MIP-1α (p = 0.03)." (PMID 28628613, 2017). "Consistently, in multi-marker analysis we found that the most relevant markers associated with presence of bacteremia were HGF, IL-15, IL-6, IP-10, MIG and MIP-1-α and additionally, G-CSF, IFN-γ, RANTES." (PMID 28628613, 2017). "Subjects with detectable bacteremia had lower levels of HGF (p = 0.005), IL-15 (p = 0.002), IL-6 (p = 0.05), IP-10 (p = 0.008), MIG (p = 0.03) and MIP-1α (p = 0.03) compared to subjects without bacteremia." (PMID 28628613, 2017).
benign ovarian tumor (2 papers, 2017 to 2019). "When comparing OC with benign ovarian tumours, six markers had statistically different expression (osteopontin, leptin, follistatin, PDGF-AB/BB, HGF, FGF-basic)." (PMID 28075407, 2017).
benign prostate hyperplasia (2 papers, 2018 to 2025). "Higher HGF plasma levels also correlate with metastatic PCa and decreased overall survival, and HGF expression is greater in PCa compared to benign prostate hyperplasia (BPH)." (PMID 40723207, 2025).
bladder tumor (2 papers, 2008 to 2014). "Finally, short variants of the deoxyadenosine tract element located in the HGF promoter associated with enhanced HGF expression were found in 37 of 70 bladder tumor specimens and correlated significantly with higher tumor grade, although the cell of origin was not identified." (PMID 25534569, 2014). "Thus, our data suggests a functional role of HGF in MGH bladder tumors." (PMID 18549507, 2008).
bronchioloalveolar carcinoma (2 papers, 2023 to 2024). A well or moderately differentiated morphologic variant of lung adenocarcinoma characterized by tumor growth along the alveolar structures without stromal, vascular, or pleural invasion. "Elevated levels of HGF in bronchoalveolar lavage fluid are associated with poorer clinical outcomes in bronchioloalveolar carcinoma patients." (PMID 39228012, 2024). "Elevated levels of HGF in bronchoalveolar lavage fluid are associated with poorer clinical outcomes in patients with bronchioloalveolar carcinoma." (PMID 37533853, 2023). "Similarly, in bronchioloalveolar carcinoma, tumour‐infiltrating neutrophils produce HGF, which interacts with c‐met receptors on tumour cells to enhance tumour cell migration." (PMID 39228012, 2024). "Similarly, in bronchioloalveolar carcinoma, tumor-infiltrating neutrophils produce HGF, which promotes the migration of tumor cells through its interaction with the c-met receptor on tumor cells." (PMID 37533853, 2023).
Buerger’s disease (2 papers, 2012 to 2025). "Recent trials with HGF showed its safety yet insignificant beneficial effects in critical limb ischemia and moderate efficacy in Buerger’s disease." (PMID 22719942, 2012).
cardiomyopathy (2 papers, 2013 to 2022). A disease of the heart muscle or myocardium proper. "In addition, HGF also improves heart functionality and promotes the proliferation of myocardial progenitor cells in doxorubicin-induced cardiomyopathy." (PMID 36293268, 2022).
carotid atherosclerosis (2 papers, 2016 to 2018). A thickening and loss of elasticity of the walls of carotid arteries that occur with formation of atherosclerotic plaques. "Another study reported a significant correlation between increased HGF concentration and carotid atherosclerosis." (PMID 26818627, 2016). "Furthermore, increased HGF concentration significantly correlates with carotid atherosclerosis." (PMID 26818627, 2016).
cerebrovascular disease (2 papers, 2018 to 2021). "Association of HGF with magnetic resonance imaging (MRI) markers of cerebrovascular disease (CeVD) in CIND and AD." (PMID 29410622, 2018).
cholestatic jaundice (2 papers, 2014 to 2024). "Interestingly, HGF is known to have potential anti-necrotic and anti-apoptotic effect on hepatocytes in cholestatic jaundice and rescues them from damage." (PMID 24642599, 2014).
chondrosarcoma (2 papers, 2013 to 2023). A malignant cartilaginous matrix-producing mesenchymal neoplasm arising from the bone and soft tissue. "Our data suggested that expression of HGF is associated with a metastatic phenotype of chondrosarcoma cells." (PMID 23320110, 2013). "The elucidation of the HGF-mediated signaling pathway sheds light on the mechanism underlying human chondrosarcoma metastasis and may lead to the development of effective therapy in future." (PMID 23320110, 2013). "Thus, expression of HGF was associated with an invasive and/or metastatic phenotype of chondrosarcoma cells." (PMID 23320110, 2013). "Taken together, these data suggest that activation of the c-Met receptor, PI3K, Akt, and PKCδ are required for HGF-induced NF-κB activation in human chondrosarcoma cells." (PMID 23320110, 2013). "Here, we found that human chondrosarcoma tissues demonstrated significant expression of HGF, which was higher than that in normal cartilage." (PMID 23320110, 2013). "We also provided evidence that the mRNA level of HGF in chondrosarcoma patients were higher than in normal cartilage and normal bone." (PMID 23320110, 2013). "We found that the expression of HGF in tissue from chondrosarcoma patients was significantly higher than in normal cartilage (arrow shows the HGF staining)." (PMID 23320110, 2013). "To elucidate a link between HGF expression and chondrosarcoma cell migration, we next examined the migratory activity of human chondrosarcoma by using the Transwell assay." (PMID 23320110, 2013). "As a first step, we examined human chondrosarcoma patients for expression of HGF using immunohistochemistry." (PMID 23320110, 2013). "Using immunohistochemistry, we showed that the protein expression levels of HGF in chondrosarcoma patients were significantly higher than those in normal cartilage." (PMID 23320110, 2013). "Taken together, our results indicated that HGF enhances migration of chondrosarcoma cells by increasing MMP-2 expression through the c-Met receptor/PI3K/Akt/PKCδ/NF-κB signal transduction pathway." (PMID 23320110, 2013). "cMET has been reported to facilitate migration of chondrosarcoma cell lines upon HGF interaction." (PMID 36622753, 2023). "In addition, the qPCR results also showed that the HGF mRNA expression levels in chondrosarcoma patients were higher than in normal cartilage as well as in normal bone." (PMID 23320110, 2013). "Moreover, directly-administered exogenous HGF promoted cell migration, invasion, and wound healing activity in chondrosarcoma cells." (PMID 23320110, 2013). "We therefore, hypothesized that any of these MMPs may be involved in HGF-directed chondrosarcoma cell migration." (PMID 23320110, 2013). "Whether other transcription factors are involved in HGF-induced MMP-2 expression in chondrosarcoma needs further examination." (PMID 23320110, 2013). "Furthermore, the wound-scratching assay demonstrated that HGF increased wound healing activity in human chondrosarcoma cells." (PMID 23320110, 2013). "In this study, we hypothesized that HGF may help to direct the metastasis of chondrosarcoma cells." (PMID 23320110, 2013). "Therefore, HGF promoted migration of human chondrosarcoma cells through up-regulation of MMP-2." (PMID 23320110, 2013). "However, little is known about the expression of HGF in human chondrosarcoma cells." (PMID 23320110, 2013). "Together, these results indicated that downregulation of SULF1 enhances the complex formation of cMET, HGF, and CD44, consequently to increase the downstream survival signaling to promote tumorigenesis of chondrosarcoma." (PMID 36622753, 2023). "Our study demonstrated that HGF increases the activity of MMP-2 via c-Met receptor-, PI3K-, Akt-, PKCδ-, IKKα/β-, and NF-κB-dependent pathways and enhanced the migration of human chondrosarcoma cells." (PMID 23320110, 2013). "Here we show that HGF increases migration and up-regulates MMP-2 expression in human chondrosarcoma cells." (PMID 23320110, 2013).
chondrosarcoma (continued). "Stimulation of human chondrosarcoma cells (JJ012 and SW1353 cells) with HGF increased migration activity dose-dependently." (PMID 23320110, 2013). "Based on these results, HGF appears to act through a signaling pathway, involving PI3K, Akt, and PKCδ to enhance cell motility and MMP-2 expression in human chondrosarcoma." (PMID 23320110, 2013). "Here, we also showed that the interaction between HGF and c-Met is very important for MMP-2 up-regulation and cell motility of human chondrosarcoma cells." (PMID 23320110, 2013). "In this study, we found that HGF induced MMP-2 expression and secretion in human chondrosarcoma cells." (PMID 23320110, 2013). "We also found that HGF increased the migration and expression of matrix metalloproteinase (MMP)-2 in human chondrosarcoma cells." (PMID 23320110, 2013). "Therefore, an interaction between HGF and c-Met appears to be very important for cell migration and MMP-2 expression in human chondrosarcoma." (PMID 23320110, 2013). "We also established cells expressing HGF-shRNA to confirm whether HGF mediated cell migration and MMP-2 expression in human chondrosarcoma cells." (PMID 23320110, 2013). "Therefore, the NF-κB binding site is likely to be an important site for HGF-induced MMP-2 expression and cell migration in human chondrosarcoma." (PMID 23320110, 2013). "However, the effect of HGF on migration activity of human chondrosarcoma cells is not well known." (PMID 23320110, 2013). "However, the effect of HGF on migration activity in human chondrosarcoma cells is not well known." (PMID 23320110, 2013).
choroidal neovascularization (2 papers, 2018 to 2020). An eye disorder described by the growth of new blood vessels that originate from the choroid through a break in the Bruch membrane into the sub–retinal pigment epithelium (sub-RPE) or subretinal space. "To note, it was reported that HGF correlated with CNV progression in animal laser model of choroidal neovascularization (CNV); however, clinical data failed to exhibit HGF levels in vitreous of AMD patients." (PMID 30651740, 2018).
Chronic myeloid leukemia (2 papers, 2014 to 2021). "Hepatocyte growth factor (HGF) is an angiogenic and autocrine growth regulator in chronic myeloid leukemia, which basophils were identified to be a major source in these patients." (PMID 34884995, 2021).
colonic diseases (2 papers, 2025). "Summarizing these results, we identified 5 proteins (CCL20, CXCL1, CXCL11, HGF, and IL-24) with increased abundance in colonic diseases, irrespective of the disease entity (colonic CD and UC) that significantly correlated with both, tissue gene expression and inflammatory severity." (PMID 40291692, 2025).
Corneal opacity (2 papers, 2018 to 2022). A reduction of corneal clarity. "Given the detrimental aftermath of corneal opacity following keratitis, understanding the effect of HGF administration in suppressing keratitis-induced corneal opacity will be of high clinical benefit." (PMID 35017561, 2022). "Here, we demonstrate the capacity of HGF to suppress keratitis-induced corneal opacity formation to preserve corneal transparency, which is essential for optimal vision." (PMID 35017561, 2022). "In this study, we developed and utilized a novel murine model of corneal opacity formation following LPS-induced keratitis to test the effect of topical HGF administration on secondary corneal opacity." (PMID 35017561, 2022). "The results of this study demonstrate that delivery of BMP7+HGF genes into stromal fibroblasts/keratocytes via nanoparticle (PEI2-GNP) significantly reduced corneal opacity by 3 weeks post injury in a preclinical rabbit model of corneal fibrosis." (PMID 29490341, 2018). "In summary, our data derived from the new murine model of LPS-induced keratitis demonstrate that topical application of HGF prevents the progression of keratitis-induced corneal opacity and inflammation by suppressing α-SMA and pro-inflammatory cytokine expression and restoring corneal architecture." (PMID 35017561, 2022).
degenerative disc disease (2 papers, 2009 to 2020). "In this study, they found that changes in HGF levels were uniquely correlated with pain and disability in patients with spinal stenosis and degenerative disc disease." (PMID 33218127, 2020). "An in vivo study demonstrated that HGF-loaded gel injected into the degenerative discs of rat tail models retards disc degeneration, as revealed by magnetic resonance imaging, histological, and immunohistochemical evaluation." (PMID 33218127, 2020). "However, the expression of HGF and c-Met in the human intervertebral disc tissue, and changes in their expression during disc degeneration were not evaluated." (PMID 33218127, 2020).
embryonal carcinoma (2 papers, 2020 to 2023). A non-seminomatous malignant germ cell tumor characterized by the presence of large germ cells with abundant cytoplasm resembling epithelial cells, geographic necrosis, high mitotic activity, and pseudoglandular and pseudopapillary structures formation. "Herein, we report that HGF immunoreactivity is more evident in the microenvironment of embryonal carcinoma biopsies with respect to seminomatous ones, indicating a tumor-dependent modulation of the testicular niche." (PMID 33212946, 2020). "To study the pathway triggered by HGF on embryonal carcinoma cells, we stimulated NT2D1 cells in vitro with HGF and inhibited specific pharmacological adaptor proteins." (PMID 33212946, 2020). "Notably, we also demonstrated that NT2D1 non-seminomatous cells (derived from an embryonal carcinoma lesion) increase their proliferation, migration, and invasion in response to HGF." (PMID 33212946, 2020). "Even if the embryonal carcinoma cells from patients are positive for HGF, NT2D1 cells do not secrete or express this factor, and this observation again highlights the importance of the microenvironment in the modulation of embryonal carcinoma cellular physiology." (PMID 33212946, 2020).